PRKDC (protein kinase, DNA-activated, catalytic subunit)
Diseases named in the same sentence as PRKDC in open-access papers (continued):
Sharing a sentence is not in itself a finding about the gene and the disease.
tumor (335 papers, 2000 to 2026). "In conclusion, the therapeutic potential of DNA-PKcs inhibition is shaped by complex molecular determinants, including tumor-specific PRKDC mutation profiles, compensatory signaling within the PIKK family, and synergistic interactions with DDR deficiencies." (PMID 40940882, 2025). "PRKDC mutations are linked to higher tumor mutational burden and better respond to immune checkpoint inhibitors, suggesting its potential as a predictive biomarker for immunotherapy." (PMID 39013964, 2024). "Enrichment of tumor immunogenicity microenvironments was found in solid tumors harboring PRKDC mutations, such as NK cells, CD8+ T cells, and chemokines." (PMID 38898995, 2024). "Elucidating the molecular mechanisms underlying PRKDC promotes tumor progression is a primary focus of ongoing research efforts." (PMID 38732044, 2024). "Tumor samples with stop-gain mutations in Exon 21 of PRKDC had a lower level in this gene, although the statistical significance was nonsense due to the small sample size and interclass numerical differences." (PMID 37854190, 2023). "The mutation rates of PRKDC and the expression levels of DNA‐PKcs vary significantly in various tumours." (PMID 37002788, 2023). "It had been reported that tumor patients with PRKDC mutation tended to have a more robust response to immunotherapy, illustrating that PRKDC contributed to malignancy by suppressing immunity." (PMID 38093288, 2023). "In summary, all these data suggested a broad association between high PRKDC expression and tumor immunity." (PMID 35801800, 2022). "Having demonstrated the tumor-specific DEGs of Cluster C1, the prior role of PRKDC was found to be associated with CD8 Tem and CTL infiltration levels in eHCC." (PMID 34745960, 2021). "Mutations of FGFR3, STAG2, and PRKDC were significantly associated with tumor risk stage (P < 0.05)." (PMID 33407469, 2021). "PRKDC is a critical component of DNA repair machinery, and its expression is implicated in tumour progression, metastasis and migration." (PMID 34366863, 2021). "In the context of PRKDC dysregulation, structural alteration results in their genomic mutation and substantial tumor-regulating roles in eHCC pathogenesis." (PMID 34745960, 2021). "Meanwhile, we noted a significant increase of PRKDC expression between eHCC and non-tumor samples, which was associated with single-nucleotide polymorphism (SNP)." (PMID 34745960, 2021). "Here, we found that PRKDC mutation often co‐exists with other DNA damage repair deficiencies and is associated with an increased tumor mutation burden, an inflamed tumor microenvironment, and a good response to immune checkpoint inhibitors." (PMID 32502294, 2020). "We aimed to investigate the association between PRKDC mutations and tumor mutation burden (TMB), tumor microenvironment (TME), and response to ICI." (PMID 32502294, 2020). "Further, solid tumors harboring PRKDC mutations were enriched in tumor immunogenicity microenvironments, such as CD8+ T cells, NK (natural killer) cells, and chemokines." (PMID 33207636, 2020). "Additionally, PRKDC has been implicated in tumor cell resistance and plays a crucial role in regulating cell cycle progression and chromosomal segregation." (PMID 38732044, 2024). "We applied the TIMER to identified the interlink of PRKDC and the immune infiltration in assorted tumors, and the SangerBox online platform was adopted to find out the relevance between PRKDC and immune checkpoint genes, tumor mutation burden, and microsatellite instability in tumors." (PMID 35801800, 2022). "Circ-PRKDC is also associated with lymph node metastasis and tumor size." (PMID 35513849, 2022). "Radiation exposure itself can induce a surge in DDR gene expression, including PRKDC, enabling tumor cells to repair radiation-induced double-strand breaks rapidly." (PMID 40725389, 2025).
tumor (continued). "Analysis of publicly available GBM patient datasets from GBMseq showed cells with elevated PRKDC expression were concentrated in malignant cells within the tumor core and periphery." (PMID 41271669, 2025). "The subtype characterized by the cell cycle can theoretically be targeted using PRKDC inhibitors to suppress tumor cell proliferation." (PMID 39762212, 2025). "The PRKDC gene encoding DNA-PKcs is a critical component of the DNA damage repair (DDR) pathway, and mutations in the tumor DDR pathway can serve as important biomarkers for a response to checkpoint-based immunotherapies." (PMID 39436696, 2024). "There is growing interest in unraveling the molecular mechanisms through which PRKDC facilitates tumor progression." (PMID 38732044, 2024). "We further analyzed the exome sequencing data set for Tumor Mutation Burden (TMB) and Neoantigen Load and categorized patients for PRKDC expression as either normal (WT) or altered." (PMID 39436696, 2024). "PRKDC gene mutations are also related to biomarkers that predict the efficacy of immunotherapy, such as microsatellite instability (MSI) and tumor mutation load." (PMID 38898995, 2024). "We further evaluated the impacts of MTHFD2, TYMS, and MTR on tumor cell proliferation under PRKDC overexpression conditions." (PMID 39039072, 2024). "We identified differentially expressed genes (DEGs) between Chr8 polyploid cells and non-tumor cells and determined that the PRKDC gene plays a crucial role in promoting the gain of Chr8 in EOC." (PMID 38732044, 2024). "Consistently, validation within the independent LUAD cohort (n = 70) of this study further supported the findings that PRKDC expression in tumor tissues was upregulated and increased PRKDC levels correlated with poor patient survival." (PMID 39660143, 2024). "The results revealed that compared to HMCB with MTHFD2-OE or TYMS-OE, PRKDC-OE cells that overexpressed with MTHFD2 or TYMS showed significantly elevated tumor cell proliferation." (PMID 39039072, 2024). "Molecular tumor testing revealed pathogenic mutations with low VAF in KRAS, ARID1A, BCORL1, and PRKDC." (PMID 37966258, 2023). "In a recent study, PRKDC mutation was found to be related to higher TMB, elevated mRNA levels of immunity-related genes as well as improved response to ICI treatments in tumor individual." (PMID 35801800, 2022). "Circ_0082182, circ-PRKDC, circ5615, and circ_0005075 are significantly correlated with advanced tumor-node-metastasis (TNM) stage in CRC." (PMID 35513849, 2022). "When examining tumor samples, one sample showed a stop-gain mutation in PolE as well as mutations in DNA-dependent protein kinase catalytic subunit (PRKDC or DNA-PK)." (PMID 35326618, 2022). "When comparing expression levels of tumor and normal samples, expression of PRKDC, BRCA2, and ATM genes was higher in the tumors." (PMID 35054819, 2022). "TIICs from tumor microenvironment (TME) are correlated with initiation, progression or metastasis of tumor, so we explored the coefficient of TIICs and PRKDC expression in diverse tumors of TCGA by using TIMER database." (PMID 35801800, 2022). "Apart from KRAS and PIK3CA, other genes preferentially altered in the right-sided primary tumor sites, such as PRKDC, ERBB3, BCLAF1 and NOTCH1, have been reported to be correlated with poor prognosis or migration in CRC." (PMID 34281583, 2021). "Lumican in PRKDC tissues was reported to be higher at the protein level, and further correlations between the lumican protein and tumor grading, OS, and organ and lymph node metastasis status were also found." (PMID 34977258, 2021). "This interaction not only enhances PRKDC promoter binding and transcription but may also establish a self-reinforcing loop through Sp1 phosphorylation by DNA-PKcs, thereby promoting tumor aggressiveness and therapy resistance." (PMID 40940882, 2025).
tumor (continued). "Taking advantage of our multi-omics studies, we further elucidated the mechanism by which PRKDC might promote tumor cell proliferation through its cis-effect and collaborate with ATM and ATR." (PMID 39039072, 2024). "Further proteogenomic analysis combined with functional experiments reveals that the cis-effect of PRKDC amplification may lead to tumor proliferation through the activation of DNA repair and folate metabolism pathways." (PMID 39039072, 2024). "PRKDC expression level was lower in adjacent normal specimens compared that of tumor tissues." (PMID 38627727, 2024). "The combined use of PRKDC and CDK4 inhibitors most significantly decreased the proliferation of PDC_PRKDCAmp&CDK4Amp cells, demonstrating that PRKDC could enhance the ability of CDK4 to promote tumor cell proliferation in the S-III subtype." (PMID 39039072, 2024). "Integrative analysis combined with functional experiments illustrated that PRKDC amplification might lead to tumor proliferation by activating the DNA repair process and folate metabolism pathway." (PMID 39039072, 2024). "Furthermore, we summarized that the risk score is strongly related to tumor recurrence in BRCA database (p = 0.01), but only HSPA8 and PRKDC performed remarkable expression difference in the recurrent tumor and primary tumor (NS, p < 0.01)." (PMID 37051596, 2023). "Our results suggest PRKDC as a new key gene driving tumor heterogeneity." (PMID 35054819, 2022). "The PRKDC expression level was shown a positive correlation with tumor-infiltrating immune cells." (PMID 35801800, 2022). "RAD21, BOP1, POLR2E, and PRKDC were mainly expressed in tumor cells, RIPK2 was mainly expressed in monocytes, MAP2K2 was mainly expressed in tumor cells and macrophages, NBN was mainly expressed in macrophages and monocytes, and GPX4 was mainly expressed in tumor cells and T cells." (PMID 36212155, 2022). "Finally, PRKDC plays a major role in nonhomologous end-joining DNA repair, which is an important factor for tumor progression and metastasis; in fact, PRKDC is considered an emerging therapeutic target in cancer." (PMID 36038612, 2022). "Overall, tumor tissue presented a higher degree of PRKDC expression than adjacent normal tissue." (PMID 35801800, 2022). "In addition, knockout PRKDC has shown the ability to enhance anti-PD-1 antibody treatment in tumor models." (PMID 34745960, 2021). "The same group showed that PRKDC, as a transcriptional regulator, might promote tumor initiation and progression." (PMID 27811370, 2016). "Importantly, the dual PI3K/mTOR inhibitor, BEZ235, has displayed robust anti-PRKDC activities and inhibition of tumor growth in pre-clinical mouse models; CC-115 also has a similar mTOR/PRKDC dual inhibition activity." (PMID 25495526, 2014). "Importantly, we found that PRKDC could inhibit the tumor-suppressive function of ZBTB38, as PRKDC knockdown resulted in the increase of DKK1 expression and enhanced the tumor-suppressive function of ZBTB38." (PMID 34697293, 2021). "In addition, knockdown of PRKDC significantly increased the CDDP-induced tumor suppression." (PMID 32661323, 2020). "Interestingly, mining of publically-available data suggests that the expression of ATR (ATR) and DNA-PKcs (PRKDC) may be tandemly regulated in certain tumours." (PMID 26486089, 2015). "However, various tumor types have been associated with elevated PRKDC mRNA- and/or DNA-PKcs levels." (PMID 26716839, 2015). "Inhibition of PRKDC with the ATP-competitive inhibitor KU57788 reversed resistance, restoring TMZ sensitivity and impairing tumor growth in vivo." (PMID 41271669, 2025). "Single-cell suspensions from tumor-bearing brains were processed by Drop-seq and analyzed with a custom Seurat v3 workflow to quantify LMNA, PRKDC, and their co-expression." (PMID 41271669, 2025).
tumor (continued). "For this purpose, we transfected the MTHFD2, TYMS, and MTR overexpression or knockdown vectors into the PRKDC-overexpressing HMCB cell line (PRKDC-OE-HMCB), respectively, and exanimated the tumor cell proliferation rates." (PMID 39039072, 2024). "ESTIMATE results suggested that patients with higher PRKDC expression had a higher stromal score, higher ESTIMATE score and lower tumor purity." (PMID 38627727, 2024). "PRKDC, XRCC6, XRCC5 and PARP1 were significantly downregulated in tumor tissue of mice treated with ESCs and ESC-CM compared with those of mice treated with PBS." (PMID 38654216, 2024). "These genes were distributed in multiple pathways, and some of them, such as MET (ranked 1st), PRKDC (ranked 8th), EXO1 (ranked 14th), and TM4SF1 (ranked 25th), have been reported to promote tumor cell proliferation." (PMID 32995120, 2020). "The immunohistochemistry (IHC) results demonstrated that DYNC1H1, GTPBP4, PRKDC, RBM19, SF3B4, SPATS2 and TAF9 were significantly increased in HCC tumor cells compared to normal hepatocytes." (PMID 33411682, 2020). "This analysis revealed significant upregulation of five genes, (XRCC6, XRCC4, PRKDC, XRCC4, and PAXX) and downregulation of two (LIG4 and NHEJ1) NHEJ pathway genes, in tumor tissues compared to the normal tissues." (PMID 33195430, 2020). "Herein, we report identification of a synthetic lethality link between PRKDC and MYC through pooled shRNA screening and demonstrate inhibition of PRKDC preferentially kills MYC-overexpressing tumor cells." (PMID 25495526, 2014). "To confirm inhibition of PRKDC preferentially kills SCLC tumor cells with MYC overexpression, we used shRNAs to knockdown PRKDC." (PMID 25495526, 2014). "Both increased CD8a and HLA-A expression negatively correlated with PRKDC expression, suggesting that decreased DNA-PK expression and activity may promote CD8 tumor infiltration." (PMID 39436696, 2024). "We also analyzed the relationship of NHEJ pathway-related genes expression and tumor metastasis of UVM patients in a BioStudies database and found that expression of XRCC6, PRKDC and PARP1 was significantly higher in patients with metastasis than in those without metastasis." (PMID 38654216, 2024). "Furthermore, tumor cells (OE-Control-HMCB, PRKDC-OE-HMCB, sh-Control-HMCB, and PRKDC-KD-HMCB) were treated with 5-FU." (PMID 39039072, 2024). "There was a strong negative relevance between PRKDC and tumor purity in KIRC, showing that PRKDC is relatively abundant in the TME." (PMID 35801800, 2022). "Transcriptome analysis suggests the enhanced DSB repair in tumor cells in the OB can be attributed to an increased expression of a group of genes (MRE11, XRCC5, XRCC6 and PRKDC) essential to the NHEJ pathway of DSB repair, which is a critical determinant of radiosensitivity." (PMID 36482431, 2022). "Not surprisingly, the PRKDC genetic alteration is emerging as a predictive biomarker and drug target for anti-tumor immunotherapy in various malignancies." (PMID 34745960, 2021). "In-Patient 2, non-canonical deleterious variants in FOXJ1, PRKDC, and TTN were detected in ~100% CCF across all tumor samples." (PMID 34400647, 2021). "Consistent with the Oncomine analysis, comparison of all available normal (n = 41) and tumor tissues (n = 469) revealed overexpression of XRCC6, XRCC5, PRKDC, XRCC4, and PAXX in tumors compared to normal tissues, while LIG4 and NHEJ1 displayed lower expression in the tumor tissues." (PMID 33195430, 2020).
tumor (continued). "In the same xenograft tumor model, another shRNA (short hairpin RNA) and aptamer A10-3 to PSMA conjugate also exhibited biological activity (65% inhibition of the PRKDC gene), but tumor regression occurred after two intratumoral injections only in combination with ionizing radiation." (PMID 31105570, 2019). "Furthermore, the PCNA, PRKDC and RAD21 module is important to DNA repair as it also helps to suppress tumours." (PMID 23002138, 2012). "Notably, compared with adjacent nontumor tissues, PRKDC expression in tumor tissues in LUAD was markedly upregulated." (PMID 39660143, 2024). "However, analysis of 41 paired normal and tumor tissues revealed significant overexpression of only XRCC5, PRKDC, and PAXX genes in tumor tissues compared to the normal colon (respectively), while LIG4 and NHEJ1 still displayed reduced expression (respectively)." (PMID 33195430, 2020). "PRKDC mRNA expression levels in two independent neuroblastoma tumor datasets were significantly higher than the expression levels in a compiled library of normal tissues and nonmalignant adrenal glands (the main primary tumor site)." (PMID 26716839, 2015). "Out of 11 genes associated with the non-homologous end joining, 4 (i.e., XRCC4, PRKDC, FEN1, and DCLRE1C) display significantly higher expressions in OS tumor samples than normal controls while DNTT has no detectable expression in normal controls." (PMID 35013466, 2022). "However, the degree of PRKDC expression in LIHC and THCA was independent of tumor purity, indicating that it was expressed equally among tumor cell and the TME." (PMID 35801800, 2022).
infection (51 papers, 2011 to 2025). The state of being infected such as from the introduction of a foreign agent such as serum, vaccine, antigenic substance or organism. "Four independent risk factors, aGVHD, infection and PRKDC, were screened by multifactorial analysis, and a prediction model was established focusing on these genes, which showed good prediction accuracy." (PMID 37002788, 2023). "Furthermore, nomograms based on aGVHD, infection and PRKDC proved more effective in assessing kidney function after transplantation." (PMID 37002788, 2023). "To test the roles of PRKDC in transcription regulation, we knocked down PRKDC gene expression by RNA interference (RNAi) with two independent short hairpin RNAs (shRNAs) in HepG2-NTCP cells, a widely used infection cell model to study HBV." (PMID 35468873, 2022). "The additional layer of phosphoregulation during IAV infection for IAV-human PPIs, including PRKDC and AHNAK, may highlight increased functional importance of the interaction in infection." (PMID 37758692, 2023). "PRKDC may be of particular interest, since it was also found to be affected in both LTNP 008 and LTNP 010, who both had low, although detectable, levels of integrated HIV DNA after infection." (PMID 30323326, 2018). "RUVBL2, ADNP, SF3A2, CDK2, PRKDC, and NONO were particularly interesting as the increase in acetylation following SIRT2 inhibition temporally aligned with the time point of maximal interaction with SIRT2 during infection." (PMID 37916830, 2023).
kidney disorder (1 paper, 2021). A disease involving the kidney. "In addition, a search in the database ClinVar for pathogenic variants known on the single PRKDC gene did not reveal any pathogenic variants linked to kidney disorder." (PMID 34423816, 2021).
PRKDC also shares sentences with these, for which no sentence is quoted: non-small cell lung carcinoma (15 papers); leukemia (13); Fanconi anemia (9); renal cell carcinoma (9); systemic lupus erythematosus (8); ataxia telangiectasia (7); head and neck cancer (7); Sepsis (7); acute myeloid leukemia (6); esophageal cancer (6); malignant glioma (6); triple-negative breast carcinoma (6); atherosclerosis (5); endothelial dysfunction (5); oral squamous cell carcinoma (5); Ataxia (4); brain tumors (4); cardiovascular diseases (4); chronic kidney disease (4); combined immunodeficiency (4); HIV-1 infection (4); Hyperglycemia (4); metastatic cancer (4); myelogenous leukemia (4); Obesity (4); Telangiectasia (4); uterine corpus endometrial carcinoma (4); Werner syndrome (4); adenovirus infection (3); B-cell chronic lymphocytic leukemia (3).
A further 167 diseases each share a sentence with PRKDC in 3 papers or fewer.